RNU1-141P (RNA, U1 small nuclear 141, pseudogene)
Gene: Small nuclear RNA gene on chromosome 1 (218,129,795 to 218,129,952, forward strand). Ensembl gene ENSG00000201493.
Homologues: Orthologues: chimpanzee U1 (98% identical), macaque U1 (92% identical), rat LOC120093963 (71% identical), mouse Gm23294 (67% identical), rat LOC120099458 (65% identical), mouse Gm22248 (60% identical). Paralogues in human: RNU1-1 (78% identical), RNU1-2 (78% identical), RNU1-27P (78% identical), RNU1-28P (78% identical), RNU1-3 (78% identical), RNU1-4 (78% identical), RNVU1-18 (78% identical), RNVU1-29 (78% identical), RNVU1-31 (78% identical), U1 (78% identical), RNU1-89P (78% identical), RNVU1-28 (78% identical), and 134 more.